IL1B (interleukin 1 beta)
Diseases named in the same sentence as IL1B in open-access papers (continued):
Sharing a sentence is not in itself a finding about the gene and the disease.
keratitis (38 papers, 2010 to 2025). A corneal disease that is characterized by inflammation of the cornea. "In conclusion, the results of this study identify essential roles for α-hemolysin and neutrophil IL-1β secretion in keratitis caused by MRSA." (PMID 41415470, 2025). "Co-occurrence of the homozygous minor alleles (OR = 18.58; 95% CI: 6.54–52.79; p < 0.00001) or genotypes (OR = 18.58; 95% CI: 4.24–81.36; p < 0.00001) in the two associated SNPs of IL1B (rs16944 and rs1143627) were associated with increased risk of keratitis." (PMID 36422638, 2022). "In vivo, CRAMP−/− mice show increased susceptibility to Pseudomonas aeruginosa (PA) keratitis and enhanced secretion of pro-inflammatory cytokines, including IL-1β, IL-6 and TNF, in PA-infected corneas." (PMID 33468624, 2021). "IL-1β plays the most important pathogenic role in the progression of keratitis." (PMID 36362313, 2022). "IL-1β, IL-6, and IL-8 can exhibit synergistic effects in the development of keratitis, eliminating pathogens and further mediating adaptive immune response." (PMID 39869570, 2025). "In the context of fungal keratitis, miR-223 targets the autophagy-related gene ATG16L1, dampening the autophagic activity of corneal stromal cells and murine corneal tissues, exacerbating keratitis, thereby elevating IL-1β levels within the tissue." (PMID 40989245, 2025). "The impact of PL on the expression of HMGB1, LOX-1, TNF-α, IL-1β, IL-6, IL-10 and ROS in A. fumigatus keratitis was investigated using RT-PCR, ELISA, Western blot, and Reactive oxygen species (ROS) assay." (PMID 38655086, 2024). "Our previous studies showed that increasing IL-1Ra expression and/or the IL-1Ra/IL-1β balance promotes epithelial wound healing and innate corneal defense against Candida albicans and Pa Keratitis." (PMID 37371057, 2023). "Our results indicated that multiple proteins that were associated with inflammasome and pyroptosis (NLRP3, ASC, CAP1, GSDMD, IL-1β and IL-18) were highly expressed in C. albicans keratitis." (PMID 35463001, 2022). "The current study demonstrated that SNPs within IL1B and CXCL8 are associated with risk of developing all forms of keratitis or (at least a trend in) microbial keratitis (frank bacterial corneal infection)." (PMID 36422638, 2022). "In human corneal epithelial cells or mice keratitis models, P. aeruginosa upregulated the inflammasome as well as pyroptosis-associated genes and activated the NLRP3/caspase-1/IL-1β pathway." (PMID 35655803, 2022). "Taken together, these results indicate that HGF treatment suppresses corneal infiltration of inflammatory cells and their expression of pro-inflammatory cytokine IL-1β during LPS keratitis." (PMID 35017561, 2022). "Western blot analysis showed that the protein levels of ASC, cleaved CASP1, N-GSDMD, cleaved IL-1β and cleaved IL-18 were all significantly elevated in C. albicans keratitis." (PMID 35463001, 2022). "In vivo experiments showed that glycyrrhizin reduced the expression of HMGB1, TNF‐α and IL‐1β in osteoarthritic cartilage, as reported in keratitis and necrotizing enterocolitis." (PMID 34953035, 2022). "In human corneal epithelial cells and mice models of A. fumigatus keratitis, pannexin 1 channels contributed to IL-1β expressions via NLRP3/caspase-1 inflammasome." (PMID 35655803, 2022). "The two SNPs, rs1143627 and rs16944, in IL1B were in high linkage disequilibrium in the current study, suggesting they are almost always inherited together and were more frequent in the keratitis and MK groups." (PMID 36422638, 2022). "This leads to constitutive production of IL-1β and culminates in systemic inflammation with multiple clinical manifestations including fever, skin rash, joint inflammation, and keratitis." (PMID 35406754, 2022). "Cases of keratitis with the minor genotype in SNP rs16944 (p = 0.046; OR = 4.02) of IL1B were more likely to have a higher score for severity of the disease than cases that possessed the dominant genotype." (PMID 36422638, 2022).
keratitis (continued). "Pretreatment with GSDMD siRNA via subconjunctival injection alleviated keratitis by suppressing IL-1β levels as well as neutrophil and macrophage recruitment in mice models of A. fumigatus keratitis." (PMID 35655803, 2022). "In an S. pneumoniae corneal infection model, NLRP3-dependent IL-1β secretion by neutrophils controlled their own recruitment to facilitate bacterial clearance at the expense of increased keratitis." (PMID 35406754, 2022). "The ocular response against infectious keratitis induces the secretion of several inflammatory cytokines, such as IL-1a, IL-1β, IL-6, IL-8, tumor necrosis factor α, and the infiltration of immune cells at the site of infection." (PMID 34436544, 2021). "A more recent study investigated the mechanisms by which PMNs process IL-1β in response to S. pneumoniae keratitis." (PMID 31703354, 2019). "In studies of animal models on the herpes simplex virus-infected keratitis, cytokines such as IL-1β, IL-6, IL-8, IL-10, IL-12, and IFN-γ were demonstrated to play a predominant role in disease development." (PMID 29673332, 2018). "Two SNPs in IL1B, rs1143627 and rs16944, occurred more commonly in all cases of keratitis, and even though the statistical power would have been reduced due to the decrease in sample size, these differences also occurred when only cases of microbial keratitis were compared with controls." (PMID 36422638, 2022). "Likewise, another study showed that glycyrrhizin reduced HMGB1, TLR4, IL‐1β and IL‐12 and was protective against keratitis." (PMID 34953035, 2022). "Preventing the production of IL-1β during P. aeruginosa keratitis by silencing the gene for ﻿the inflammasome NLRC4, inhibiting caspase-1 production (either using gene knockout mice or antibodies), or administering IL-1Ra (a natural inhibitor of IL-1β) reduces the clinical pathology of keratitis." (PMID 36422638, 2022). "As Daniel reported, inflammatory factors, such as IL-1b and LIX were elevated between day 1 and 4 weeks after the blast, and LIX was associated previously with neutrophil infiltration to the stroma and keratitis." (PMID 34631761, 2021). "In addition to IL-6 and IL-8, the chemokine IL-1β is also a critical mediator of the innate host response to P. aeruginosa keratitis." (PMID 31703354, 2019). "Moreover, Il6 and Il1b expressions, which contribute to S. aureus clearance in skin wound sites and in keratitis, were significantly higher in miR‐223Y/− wounds." (PMID 30171089, 2018). "Increased IL-1β and IL-6 are the specific inflammatory signals for keratohelcosis and keratitis." (PMID 29673332, 2018). "Data presented here lend further support to this notion and extend recent observations on the importance of neutrophil-derived IL-1β in selected infections, such as Staphylococcus aureus skin abscesses and Pseudomonas aeruginosa or Streptococcus pneumoniae keratitis." (PMID 27509078, 2016). "Taken together, the findings of our study indicate that the interaction of PRRs and A. fumigatus could be concerned with irreversible change of keratitis via cytokine expression such as IL-6 and IL-1β in concert with IDO expression." (PMID 26361229, 2015). "Another recent study on mouse fungal keratitis demonstrated that inhibiting GSDMD expression with GSDMD siRNA could improve the outcome of keratitis, which was characterized by decreased corneal inflammation, suppressed neutrophil and macrophage infiltration and reduced production of IL-1β." (PMID 35463001, 2022). "Similarly, there were higher levels of IL-1β, IL-6 and IL-8 cytokines were quantified in keratitis caused by Gram-negative bacteria." (PMID 33208864, 2020). "In summary, we proved that thymol played a protective part in A. fumigatus keratitis by cutting down inflammatory cells aggregation, downregulating the TLR4/ MyD88/ NF-kB/ IL-1β signal expression and reducing necroptosis and pyroptosis." (PMID 36517045, 2023).
keratitis (continued). "Some scholars have found that LXA4 attenuates the inflammatory response by downregulating the production of the proinflammatory factors IL-1β, TNF-α, and IL-6 via the Fpr2 receptor in Aspergillus fumigatus keratitis mouse models." (PMID 36544058, 2023). "In mice models of S. pneumoniae keratitis, the NLRP3 inflammasome (NLRP3, ASC, and caspase-1) was proven to be essential for cleavage and secretion of corneal neutrophil-derived IL-1β and bacterial clearance." (PMID 35655803, 2022). "Particularly, recent report indicated that neutrophil is the predominant cell in murine model of keratitis regarding NLRP3/ASC inflammasome and caspase-1 activation, and subsequent IL-1β processing." (PMID 31270454, 2019). "IL-1β, a pro-inflammatory cytokine activated by NLRP inflammosome signals, has been shown to be elevated in P. aeruginosa keratitis." (PMID 23358433, 2013). "Topical miR-204-5p after LPS-induced keratitis in mice failed to suppress Vegfa, Angpt1, Il-1β, and Tnf-α or rescue Pax6 levels in contrast to in vitro results, although it significantly reduced the inflammatory infiltrate in the cornea." (PMID 39488562, 2024). "Specifically, the levels of IL1B, 1L8, and IL15 were found to be significantly decreased in genipin-treated corneas in the S. aureus (p = 0.005 for IL1B, p = 0.019 for IL8, p = 0.001 for IL15) and the P. aeruginosa (p = 0.013 for IL1B, p = 0.001 for IL8, p = 0.001 for IL15) keratitis model." (PMID 37108070, 2023). "When the NLRP3 inflammasome is activated, a large amount of the proinflammatory cytokines IL-1β and IL-18 are released through GSDMD pores, which may trigger and aggravate corneal inflammation and result in enhanced ocular injury in C. albicans keratitis." (PMID 35463001, 2022). "During corneal infections, IL-1β, IL-6, IL-8, and TNFα are important in the initiation of inflammatory signals and both TLR2 and TLR5 mediate microbial clearance and cytokine production during S. aureus and PA keratitis." (PMID 28796783, 2017). "Furthermore, our in vivo and in vitro data indicated that STING decreased the stromal infiltration of immune cells and the production of inflammatory cytokines including IL-1β, IL-6, MIP-2, and TNF-α, suggesting that STING plays an anti-inflammatory function in PA-induced keratitis." (PMID 29922287, 2018). "However, we showed that in a murine model of P. aeruginosa keratitis, neutrophils mediate IL-1β secretion using serine proteases rather than caspase-1, although NLRP3 and ASC are reportedly expressed by neutrophils." (PMID 23750216, 2013).
liver cancer (38 papers, 2018 to 2026). An epithelial or non-epithelial malignant neoplasm that arises from the liver. "Minor activation of pyroptosis induces a minority production of IL-1β which promotes the proliferation of liver cancer, while severe activation of this pathway causes the death of HCC cells." (PMID 36763290, 2023). "The activities of plasma IL1B in liver cancer patients enrolled have been significantly affected by the level of plasma cholesterol (P < 0.001) and the test result of IL1B is a predictor variable causing the changes of serum Fe levels (P < 0.001)." (PMID 38191842, 2024). "In line with our results, depleting macrophages or neutralizing IL-1β in vivo abrogated liver cancer growth and lung metastasis, antagonizing sorafenib resistance in HCC." (PMID 38672578, 2024). "At the same time, the content of IL-1α, IL-12 P70, TNF α, IL-1β and IL-6 was significantly reduced, and the content of IL-10 was significantly increased like in the previous liver cancer model." (PMID 34976592, 2022). "Two different concentrations (20 μg/ml and 40 μg/ml) of Tribulusterrestris methanolic plant extract were subjected to assess the protein concentration of TNF-α and IL-1β through ELISA in the HepG-2 liver cancer cell line." (PMID 36577761, 2022). "Similar to liver cancer, IL-1β induced EMT in PDAC cell lines accompanied by COX-2 and HIF-1α overexpression." (PMID 31588122, 2019). "By screening the Human Protein Atlas database, we also found that liver cancer patients with lower expression levels of IL1β and Cab39 had higher survival rates." (PMID 31816816, 2019). "Researches showed that serum level TNF-α, IL-lα and IL-1β in liver cancer patients were significantly higher, especially higher in patients with recurrence of liver cancer." (PMID 31341840, 2019). "In liver cancer we had shown that aberrant TLR-4-TRIF-NF-κB signalling mediated cancer cell debris-induced IL-1β production." (PMID 31588122, 2019). "Cytokines such as TNF-α, IL-6, and IL-1β can increase CD55 expression in liver cancer cells." (PMID 40596619, 2025). "Multivariate logistic regression analysis showed the activities of plasma IL1B in liver cancer patients enrolled have been significantly affected by the level of plasma cholesterol (P < 0.001) and the test result of IL1B is a predictor variable causing the changes of serum Fe levels (P < 0.001)." (PMID 38191842, 2024). "Therefore, elevated levels of these inflammatory markers (i.e. IL-1β, IL-4, IL-6, IL-10, TNF-α and C-reactive protein) increase the risk of liver cancer development." (PMID 37990536, 2023). "The result shows that the injection of HDW could significantly reduce the liver lesion area and the serum levels of IL-6, IL-17, TNF-α, and IL-1β in the orthotopic liver cancer mouse model, and these results were dose-dependent to some extent." (PMID 36647454, 2023). "However, drastically low LDH was noticed in IL-1β-induced Hep2 liver cancer cells preconditioned with T. terrestris extract concentrations compared to stress." (PMID 36577761, 2022). "We speculated that in PDAC, IL-1β is released by M2 polarised TAMs, in a similar manner to found in liver cancer, and interference with its effects would be beneficial for PDAC control." (PMID 31588122, 2019). "Therefore, we inferred that PDAC cell debris was able to induce IL-1β secretion from M2 polarised macrophages, as observed in liver cancer." (PMID 31588122, 2019). "In addition, the Human Protein Atlas database showed that liver cancer patients with high expressions of IL1β and Cab39 had lower survival rates." (PMID 31816816, 2019). "IL1β has also been reported to promote the migration of liver cancer cells." (PMID 31816816, 2019). "In the liver cancer cell line (HepG2), genistein significantly promoted miR-451 expression, and both the miR-451 mimic and genistein significantly inhibited the expression of IL1β and Cab39." (PMID 31816816, 2019).
liver cancer (continued). "A total of 86 targets of the herbal compound for liver cancer were obtained, mainly five core targets of IL-6, ESR1, JUN, IL1β, and MMP9." (PMID 37680619, 2023). "In particular, we investigated the impact of IL-1β, IL-6, TNF-α, and TGF-β on PLIN5 expression in different human liver cancer cell lines." (PMID 37108378, 2023). "After liver damage occurs, hepatic macrophages secrete pro-inflammatory cytokines and chemokines, including IL-1β and TNF, activating the inflammation-tumorigenesis cascade and triggering the immune escape that fuels the development of liver cancer." (PMID 31523179, 2019). "Wei and others showed that during the development of HCC, the NLRP3 components are dysregulated depending on the disease stage, while in the inflammatory hepatic setting it copes with IL-1β and NLRP3 upregulation, and malignantly transformed liver cancer is downregulated." (PMID 36289606, 2022). "The results showed that both the aqueous and ethanol extracts (QC and QS, respectively) of Qizhu decoction significantly inhibited hepatic inflammation and liver cancer induced by diethylnitrosamine or hepatitis B virus by suppressing NF-κB signaling and decreasing the levels of TNF-α and IL-1β." (PMID 30723284, 2019). "MiR-451 and its target genes, IL1β and Cab39, may play an important role in the mechanism by which genistein inhibits NAFLD/NASH and liver cancer." (PMID 31816816, 2019).
pulmonary hypertension (38 papers, 2012 to 2025). Increased pressure within the pulmonary circulation due to lung or heart disorder. "ZC3H12A deficiency in mouse alveolar macrophages represented severe pulmonary arterial hypertension, while IL-6 and IL-1β may have served as potential targets for ZC3H12A in alveolar macrophages." (PMID 37504305, 2023). "Inhibition of PKM2 can reverse the glycolysis status of the hypertensive pulmonary arterial wall (PH-Fib), reduce its cell proliferation, and decrease the expression of IL-1β in macrophages, thus delaying the progression of pulmonary hypertension." (PMID 35967360, 2022). "For instance, astragalus polysaccharides decrease levels of the inflammatory cytokine TNF-α, IL-1β and IL-6 to resist pulmonary artery hypertension induced by MCT." (PMID 35033157, 2022). "Our study shows that NLRP‐3 is involved in regulating the expression of IL‐8 and IL‐1β in rats with pulmonary hypertension." (PMID 33295020, 2021). "The ELISA results showed that AS‐IV reduced the levels of IL‐18 and IL‐1β in the serum of rats with pulmonary hypertension, and the inhibitory effect was similar to that of MCC950 and MDL‐28170." (PMID 33295020, 2021). "Pulmonary arterial hypertension patients exhibit high levels of the cytokines IL-1β and TNFα that in the presence of TGFβ induce EndMT in pulmonary arterial ECs in vitro." (PMID 32226439, 2020). "Patients with pulmonary hypertension have increased levels of IL-1β and overexpression of proinflammatory cytokines induces pulmonary hypertension." (PMID 31718614, 2019). "Potential implications: These data implicate that IL-1β appears to have deleterious effects for the development and progression of pulmonary hypertension." (PMID 24739042, 2014). "These previous studies suggest that IL-6, TNF-α, and IL-1β may be actively involved in pulmonary hypertension." (PMID 31815093, 2019). "In addition, increased serum level of IL-1β was observed in the serum of patients with severe primary pulmonary hypertension." (PMID 22363104, 2012). "In addition, it has been suggested that overexpressed lncRNA CPS1-IT can slow down the progression of pulmonary hypertension in patients with OSAHS by modulating the transcriptional activity of hypoxia-inducible factor 1 (HIF1) to reduce the expression of interleukin-1β (IL-1β)." (PMID 40264951, 2025). "In pulmonary arterial hypertension (PAH), bulk RNA-Seq and single RNA-Seq were performed on the PAECs and HUVECs EndMT models induced by co-stimulation with TGF-β2 and IL-1β." (PMID 35740920, 2022). "In animal models of pulmonary hypertension induced by monocrotaline (MCT), the activation of P2X7 receptors is accompanied by an increase in NLRP3 inflammasome and IL-1β." (PMID 33995071, 2021). "This schematic illustrates the core mechanism in the pathogenesis of pulmonary arterial hypertension: Pulmonary vascular injury activates lung macrophages, releasing inflammatory mediators such as CCL2/CCL7, IL-1β/IL-6, and mitochondrial DAMPs into the circulatory system." (PMID 41479889, 2025). "The Nef constructs derived from HIV-pulmonary hypertensive donors demonstrated significant increases in Th1 cytokines IL-2, IL-12p70, and IFNg, as well as anti-inflammatory IL-10, but did not elicit innate immunity cytokines IL-1b or TNFa." (PMID 40559196, 2025). "In a rat model of pulmonary arterial hypertension (PAH), which was established by a single injection of monocrotaline, capsaicin pre-treatment reversed PAH, decreased the levels of macrophage/monocytes, and expression of inflammatory cytokines such as IL-1β, IL-6, and TNF-α in lungs." (PMID 36278231, 2022). "Interestingly, mice lacking NLRP3 display attenuated pulmonary hypertension and a blunted inflammasome activation with decreased caspase-1, IL-18, and IL-1β levels in response to hypoxia induced pulmonary vasoconstriction." (PMID 31915037, 2020).